NOTCH3 (notch receptor 3)
Diseases named in the same sentence as NOTCH3 in open-access papers (continued):
Sharing a sentence is not in itself a finding about the gene and the disease.
colorectal cancer (34 papers, 2012 to 2026). A primary or metastatic malignant neoplasm that affects the colon or rectum. "Genes that were significantly positively associated with Notch3 expression in colorectal carcinoma were picked out and GSEA enrichment were performed." (PMID 36647017, 2023). "In conclusion, both Notch receptors and ligands are abnormally expressed in colorectal cancer and Notch-3, Jagged-1 and Dll-4 are associated with tumor metastasis." (PMID 31198409, 2019). "Activating mutations of Notch3 are present in human T-cell acute lymphoblastic leukemia and a number of human solid tumors, including ovarian, breast and colorectal cancer." (PMID 23426998, 2013). "In addition to TET1 and RNF43, our study also identified an association between NCOA3, CREBBP, and NOTCH3 mutations and improved survival in colorectal cancer patients." (PMID 35798829, 2022). "NOTCH3 mutation was also most frequent in colorectal cancers, followed by melanoma." (PMID 35798829, 2022). "Interestingly, the rs1043994 located in NOTCH3 showed gender preference and was found to be significantly associated with colorectal cancers in males." (PMID 34257585, 2021). "As cancer risk can be influenced by differential gene expression pattern between men and women as a result of differences in their hormonal and genetic factors, the association of colorectal cancer in men could be attributed to NOTCH3 - rs1043994 variants." (PMID 34257585, 2021). "For example, DLL4 expressed by endothelial cells was shown to activate Notch signaling via Notch3 in T cell acute lymphatic leukemia and via Notch1 in colorectal cancer." (PMID 39951484, 2025). "In colorectal cancer cell lines, as well as in primary cultures of colorectal metastases, a positive link between the activation of NOTCH3 and NOTCH1 receptor has been reported." (PMID 37860822, 2023). "In the present study, we evaluated for the first time the association of NOTCH1, rs3124591; NOTCH2, rs11249433; NOTCH3, rs1043994, and NOTCH4, rs3830041 SNPs with the susceptibility of breast and colorectal cancers in Saudi population." (PMID 34257585, 2021). "We examined the genotypes of four germline SNPs residing in NOTCH1 - rs3124591, NOTCH2 - rs11249433, NOTCH3 - rs1043994, and NOTCH4 - rs3830041 to determine their association with breast and colorectal cancer risk in Saudi Arabian patients." (PMID 34257585, 2021). "Expression of Notch3 and Notch4 receptors was significantly higher in colorectal cancers compared to normal and adenoma tissues." (PMID 32211044, 2020). "Another study also confirmed a link between high levels of Notch3 and aggressive malignant colorectal cancer cell phenotype and tumor recurrence after surgical resection of CRC." (PMID 32211044, 2020). "Notch3 and Notch4 expressions were significantly higher in colorectal cancers compared to normal and adenoma tissues (Notch3: normal vs. CRC, p=0.0052, adenoma vs CRC, p=0.0018; Notch4; normal vs. CRC, p=0.0046, adenoma vs. CRC, p=0.036)." (PMID 32211044, 2020). "Notch 3 is overexpressed in a subset of colorectal cancer patients and induction of Notch 3 overexpression in colorectal cancer xenografts led to increased tumour formation." (PMID 32575680, 2020). "Notch-3 is highly expressed in metastatic carcinoma of colorectal cancer, suggesting its potential involvement in tumor metastasis." (PMID 31198409, 2019). "Indeed, NOTCH3 was shown to be overexpressed in spheroids derived from colorectal cancer cell lines (WiDr) compared to the parental cell line, confirming the implication of the NOTCH3 receptor in the maintenance of pluripotency in colorectal CSCs." (PMID 37860822, 2023). "Neurogenic locus notch homolog protein 3 (NOTCH3) is highly expressed in colorectal cancer (CRC)." (PMID 35900231, 2022).
colorectal cancer (continued). "LS180 proliferation was inhibited by blocking either APJ or Notch3, suggesting that apelin-13/APJ could promote colorectal cancer cell proliferation by modulating Notch3 pathways." (PMID 33912466, 2021). "In view of these observations, inactivation of Notch3 signaling may prove beneficial in the therapeutic outcome of colorectal cancers." (PMID 32211044, 2020). "Interestingly, results from this study also demonstrated that endothelial DLL-4 had the potential to induce colorectal cancer cell migration via Notch3 and Asef." (PMID 29104587, 2017). "It is therefore tempting to speculate that NOTCH3-Asef signaling may be connected with the invasive behavior of colorectal cancer cells." (PMID 24244701, 2013). "Moreover, the expression of NOTCH1, -3 and -4 receptors was reported to be significantly higher in colorectal cancers compared to normal and adenoma tissues, and patients overexpressing NOTCH3 and NOTCH4 receptors, and the HEY1 transcriptional target, exhibit poorer overall survival." (PMID 37860822, 2023). "However, NOTCH3 mutation was only associated with improved survival in the colorectal cancer group, though unlike NCOA3, this relationship was highly significant." (PMID 35798829, 2022). "In order to evaluate whether gender played any role in the association of NOTCH1-rs3124591, NOTCH2-rs11249433, NOTCH3-rs1043994, and NOTCH4-rs3830041 with colorectal cancers, the study subjects were grouped as males and females for counting the genotype and allele frequencies." (PMID 34257585, 2021). "As seen in OC, Epstein-Barr virus (EBV)-associated nasopharyngeal carcinoma and colorectal carcinoma (CRC), inhibition of Notch3 signaling can significantly enhance the cisplatin chemosensitivity of tumor cells, indicating the value of Notch3-targeted therapy." (PMID 34195229, 2021). "Besides calculating fold-change expression of Notch pathway genes in adenomas and colorectal cancers relative to the adjacent normal tissues, we further calculated expression of Notch3 and Notch4 by the ΔCt method using GAPDH as reference gene in normal, adenoma, and cancer tissues." (PMID 32211044, 2020). "Thus, we speculate that the NOTCH3-Asef signaling pathway may be a novel therapeutic target for colorectal cancer treatment." (PMID 24244701, 2013). "JAG1 has been reported as a target molecule of β‐catenin in colorectal cancer, and JAG1 was shown to induce NOTCH3 expression in endometrial epithelial cells." (PMID 37272232, 2023). "In colorectal cancer (CRC), NOTCH3 transcript is significantly upregulated in primary and metastatic samples, and it accelerates tumor growth." (PMID 33452458, 2021). "Linc00707 binds to miR-206 and inhibits its negative regulation against NOTCH3 and TM4SF1, promotes the proliferation and metastasis of colorectal cancer cells." (PMID 33542193, 2021). "In colon cancer forced expression of Notch3 increased the level of MUSASHI-1 (MSI-1), whereas silencing of Notch3 by shRNA reduced the MSI-1 level in both colorectal cancer cells and tumor xenografts." (PMID 29104587, 2017). "To be noted, we showed that inhibition of Notch3 had no obvious influences on colorectal cancer cell proliferation in vitro." (PMID 36647017, 2023). "A notable finding was that inhibition of Notch3 had no influences on colorectal cancer cell proliferation in vitro, whereas interfering with Notch3 significantly decreased tumor growth in vivo." (PMID 36647017, 2023). "Nuclear expression of Notch3 has been correlated with tumor recurrence and may serve as a novel predictive marker in recurrent stage II and III colorectal cancer." (PMID 29104587, 2017).
migraine (34 papers, 2008 to 2025). "Additional studies on the prevalence of migraine with aura according to NOTCH3 mutation location in Asian CADASIL populations are still needed." (PMID 40169951, 2025). "Only 2% of Notch3 mutations are associated with other neurodegenerative diseases such as the small-vessel disease of the brain, ischemic stroke, migraine, and autism." (PMID 38790158, 2024). "Associations of NOTCH3-rs1043994 synonymous variant with lacunar infarction and migraine have also been reported in Chinese and German patients, respectively." (PMID 34257585, 2021). "Loss of NOTCH3 function has been found to increase susceptibility to cortical spreading depression, causing migraine with aura also associated with ischemic stroke." (PMID 31288479, 2019). "The DNA samples from MF1 that were examined for NOTCH3 – CADASIL mutations were from individuals affected with typical migraine in a pedigree previously shown to be linked to chromosome 19p13." (PMID 19018300, 2008). "Further studies are needed to clarify the role of NOTCH3 variants in migraine." (PMID 34488620, 2021). "However, this does not discount the possibility of a role for mutations in the as yet unscreened exons in NOTCH3 in migraine susceptibility." (PMID 19018300, 2008). "More extensive sequencing of the NOTCH 3 gene that may identify novel mutations that relate to migraine should be undertaken." (PMID 19018300, 2008). "The NOTCH3 gene may also be implicated in migraine, as migraine shows some symptomatic overlap with CADASIL." (PMID 19018300, 2008). "However, given her strong history of migraines with aura and family history of the variant, she may have an increased likelihood of carrying the particular NOTCH3 variant." (PMID 40438539, 2025). "However, Liem and colleagues suggested that this could be due to a myriad of factors such as the NOTCH3 gene acting as a migraine aura susceptibility gene or an increased susceptibility to CSD." (PMID 37628876, 2023). "Some genes such as CACNA1A, NOTCH3, TREX1 and COL4A1 are associated with nystagmus or vasculopathies related to migraines." (PMID 37622929, 2023). "Based on the clinical symptoms of migraine with aura and WML on MRI, the index patient was again referred to the neurology department and analyzed for NOTCH3 mutations." (PMID 33898742, 2021). "We identify a family with migraine and WML in which some members carry a cysteine-sparing hypomorphic NOTCH3 mutation." (PMID 33898742, 2021). "In conclusion, our study reveals a family with migraine and WML carrying a cysteine-sparing hypomorphic NOTCH3 mutation." (PMID 33898742, 2021). "Choi highlighted phenotypic similarities between COL4A1 SVD and NOTCH3 mutations in CADASIL, showing that both conditions cause lacunar infarcts, cognitive deficits, intracerebral haemorrhage and migraine." (PMID 31915071, 2020). "In terms of genetic markers, mutations in CACNA1A, ATP1A2, and SCN1A are closely associated with FHM, while variants in NOTCH3 and TREX1 genes have been linked to migraine and its associated cerebrovascular diseases (e.g., cerebral arteriolar dominant disorders)." (PMID 39958329, 2025). "The NOTCH3 gene was analysed by sequencing all exons with known CADASIL mutations in a typical (non-familial hemiplegic) migraine family (MF1) that has previously been shown to be linked to C19p13." (PMID 19018300, 2008). "Our results suggest that common migraine is not caused by any known CADASIL mutations in the NOTCH3 gene of interest." (PMID 19018300, 2008). "Other frequent features included hyperreflexia (91%, 21/23), strabismus (50%, 9/18), ataxia (48%, 10/21), dysarthria (39%, 7/18), and headache (35%, 8/23), although it could not be conclusively determined if the latter corresponded to migraine, a known feature of NOTCH3-SVD." (PMID 39191170, 2024).
migraine (continued). "Finally, I think that his additional arguments related to the lack of difference in the prevalence of migraine with aura between individuals carrying a NOTCH3 gene variant and those who do not; in large population-based studies must be used with infinite caution." (PMID 40169951, 2025). "Studies from mainland China and Japan also demonstrated a low prevalence of migraine in CADASIL patients ranging from 5.3% to 27.6%, regardless of NOTCH3 mutation sites." (PMID 26308724, 2015). "Overall the results presented here do not support a relationship between NOTCH3 and common migraine." (PMID 19018300, 2008). "The NOTCH3 gene has been localised to C19p13, a region showing linkage to MF1 a typical (not FHM) migraine pedigree." (PMID 19018300, 2008).
pancreatic cancer (33 papers, 2011 to 2025). "MUC4/Y, one of the MUC4 transcript variants, was reported to be overexpressed in pancreatic cancer, in which it upregulated NOTCH3 expression, promoting tumor angiogenesis and metastasis." (PMID 37853162, 2023). "Additionally, altered BCAA metabolism in pancreatic cancer has been linked with upregulated levels of NOTCH3 and NOTCH4, suggesting their involvement in metabolic adaptations seen in this disease." (PMID 39286249, 2024). "The result of Oncomine database shows that NOTCH3 is overexpressed in lots of cancers such as bladder, colorectal, gastric, head and neck, kidney, leukemia, liver, lung, lymphoma, ovarian and pancreatic cancers compared to normal tissues." (PMID 38906903, 2024). "In vitro studies revealed that NOTCH3 promotes resistance to gemcitabine via activation of PI3K/Akt signaling in pancreatic cancer." (PMID 36749424, 2023). "NOTCH3 is known to be a mediator of resistance towards gemcitabine-based cancer treatment, at least in pancreatic cancer and non-small cell lung cancer." (PMID 36749424, 2023). "On the other hand, knockdown of miR-613 promotes the proliferation and metastasis of pancreatic cancer cells by facilitating Notch3 expression and regulating the Notch3 pathway." (PMID 36061358, 2022). "Here we showed that NSD3 silencing (by targeted shRNA) or KO (using CRISPR/Cas9 method) in pancreatic cancer cells potently inhibited H3K36m2 and expression of these oncogenic genes (Prkaa2, Myc, Irgm1, Adam12, and Notch3)." (PMID 34615858, 2021). "Several miRNAs can furthermore control the Notch pathway, e.g., miR34a and miR326 have been shown to target both Notch1 and Notch2 in gliomas and pancreatic cancer, and Notch3 3′ UTR can be targeted by miR206." (PMID 29462871, 2018). "The effect of conditioned medium from PaSCs activated with Notch3 siRNA on pancreatic cancer (LTPA) cells was also detected with CCK-8 assays and scratch experiments." (PMID 29304760, 2018). "In pancreatic cancer cells, HOTAIR plays the role of ceRNA, combines with miR-613, increased the expression of Notch3, and promoted pancreatic cancer cell proliferation, migration and invasion." (PMID 29132362, 2017). "Notch3 is expressed at a high level in human pancreatic cancer cells and acute T-cell lymphoid leukemia cells." (PMID 23599800, 2013). "A peptide fragment of Notch3 was detected in plasma from patients with inoperable pancreatic cancer, but due to wide inter-individual variation, mean levels were not significantly different compared to age-matched controls." (PMID 23226563, 2012). "Using immunohistochemistry (IHC) on a tissue array, we discovered that Notch3 was most often overexpressed in pancreas cancer, followed by Notch4." (PMID 22074495, 2011). "Using a pancreas cancer tissue microarray, we noted that Jagged1, Notch3 and Notch4 are overexpressed in pancreas tumors (26%, 84% and 31% respectively), whereas Notch1 is expressed in blood vessels." (PMID 22074495, 2011). "It has been reported that HOTAIR could regulate the expression of Notch3 by acting as ceRNA to sponge miR-613 in the context of pancreatic cancer." (PMID 33461171, 2021). "Studies have shown that NSD3-dependent genes (Prkaa2, Myc, Irgm1, Adam12, and Notch3) could exert different cancer-promoting functions in pancreatic cancer." (PMID 34615858, 2021). "Furthermore, we confirmed that inhibition of PaSC activation via Notch3 siRNA reduced the proliferation and migration of PaSC-induced mouse pancreatic cancer (LTPA) cells." (PMID 29304760, 2018). "Additionally, NOTCH3 could be identified as parameter for predicting therapy response to gemcitabine in pancreatic cancer: expression of NOTCH3 inversely correlated with therapy response and overall survival of patients treated with gemcitabine." (PMID 36749424, 2023).
pancreatic cancer (continued). "Moreover, Notch 1 expression has been related to cisplatin resistance in different types of cancers, such as head and neck squamous cell carcinoma and colon carcinoma, and Notch 3 expression has been related to gemcitabine resistance in pancreatic cancer cells." (PMID 33916610, 2021). "For instance, in pancreatic cancer, GATA2 was found to bind to the promoter regions of Notch3 and transcriptionally activate its expression, thereby promoting the metastasis of pancreatic cancer cells to the liver." (PMID 41514651, 2025). "IHF analysis was carried out on the frozen pancreatic tumour tissue sections to confirm the expression of MUC4/Y and NOTCH3." (PMID 27287498, 2016). "Consistent with the recent observation that SFK inhibition was able to decrease the active cleaved form of NOTCH1 in pancreatic cancer cells, we found that SI221 greatly decreased the cleaved form of NOTCH3 in both RD and RH30 cell lines." (PMID 25762618, 2015). "Tarextumab (OMP-59R5), a monoclonal antibody (mAb) against Notch2 and Notch3, has shown promising antitumor activity in several in vitro and in vivo models of SCLC, breast, ovarian, and pancreatic cancer that correlated with downregulation of Notch target genes." (PMID 34680255, 2021). "In the present study, we found that Notch3 was highly expressed in α-SMA-positive cells in human pancreatic tumor tissue but not in normal pancreatic cells, suggesting that Notch3 participates in PaSC activation." (PMID 29304760, 2018). "Moreover, a cross-reactive human monoclonal Notch2 and Notch3 antagonist, OMP-59R5 (Tarextumab), is effective in reducing cancer cell proliferation and the growth of breast, lung, ovarian, and pancreatic cancers." (PMID 29462871, 2018). "Also, the pancreatic cancer dataset in TCGA indicates that DLL4, NOTCH1, NOTCH2, and NOTCH3 levels do not affect survival." (PMID 35673567, 2022).